RNU6-125P (RNA, U6 small nuclear 125, pseudogene)
Gene: Small nuclear RNA gene on chromosome 1 (88,816,779 to 88,816,885, forward strand). Ensembl gene ENSG00000207234.
Homologues: Orthologues: chimpanzee U6 (99% identical), dog U6 (88% identical), rat LOC120097304 (85% identical), mouse Gm55621 (75% identical). Paralogues in human: RNU6-1060P (92% identical), RNU6-15P (92% identical), RNU6-12P (91% identical), RNU6-13P (91% identical), RNU6-31P (91% identical), RNU6-32P (91% identical), RNU6-33P (91% identical), RNU6-41P (91% identical), RNU6-1 (90% identical), RNU6-1011P (90% identical), RNU6-116P (90% identical), RNU6-17P (90% identical), and 1285 more.